ATG9A (autophagy related 9A)
Diseases named in the same sentence as ATG9A in open-access papers (continued):
Sharing a sentence is not in itself a finding about the gene and the disease.
cancer (continued). "Regarding ATG9A, the conclusions on its expression and function in cancer can also vary according to the study." (PMID 30563263, 2018). "Altogether, these data confirmed that a decrease in ATG9A expression led to the inhibition of pro-cancer phenotypes, and were therefore coherent with our in vivo data showing a high expression of ATG9A in TNBC." (PMID 30563263, 2018). "We then developed in vitro ATG9A invalidation models in the TNBC cell line MDA-MB-436 and showed that a decrease in ATG9A expression led to an inhibition of cancer phenotypes within these cells." (PMID 30563263, 2018). "Indeed, single-cell RNA-Seq demonstrated that ATG9A KO in cancer cells promoted macrophage activation towards a cytotoxic phenotype, characterized by markers such as Inos, S100a8, Lcn2, and Cox-2." (PMID 40595560, 2025). "Our findings show that ATG9A knockout sensitizes cancer cells to macrophage-mediated killing, specifically due to insufficient repair of ROS-induced plasma membrane damage, providing novel insights into the mechanism by which macrophages directly kill cancer cells." (PMID 40595560, 2025). "To determine whether ATG9A KO-induced sensitization depends on direct cancer-macrophage contact, we conducted co-culture experiments with a 0.4 μM pore insert segregating α-EphA2-CAR-Ms on top." (PMID 40595560, 2025). "In vivo experiments using subcutaneous and intraperitoneal SKOV-3 models further confirmed that ATG9A ablation enhances macrophage-mediated killing of cancer cells, suggesting that targeting ATG9A may improve responses to macrophage-based therapies." (PMID 40595560, 2025). "Similarly, promoter hypermethylation of ATG4D, ATG2B, ATG9A, and ATG9B genes has been demonstrated in most invasive ductal carcinomas (IDC), and this enhanced methylation was associated with the cancer grade, reduced gene expression, and lymph node metastasis." (PMID 40949798, 2025). "ATG9A inhibition led to an inhibition of in vitro cancer features." (PMID 33194339, 2020). "Indeed, the role of ATG9A in autophagy seems dependent on the in vitro model or the type of cancer analyzed, and appears complex in cancers." (PMID 30563263, 2018). "We found that ATG9A inhibition led to an inhibition of in vitro cancer features, suggesting that ATG9A can be considered as a new marker of TNBC and might be considered in the future as a target to develop new specific TNBC therapies." (PMID 30563263, 2018). "ATG9A has been shown to be upregulated in some carcinomas but has yet to be studied in PDAC." (PMID 27626694, 2016). "Upregulation of ATG9A has been well documented in other carcinomas." (PMID 27626694, 2016). "Therefore, it is clear that further studies would be needed to determine whether ATG9A could modify the ratio of stem cells vs. cancer cells in TNBC." (PMID 30563263, 2018). "Our screen identified ATG9A along with several ESCRT genes (UBAP1, CHMP6, and VPS25) as critical determinants of the cancer cell response to macrophages." (PMID 40595560, 2025). "We observed a significant reduction in ATG9A KO and UBAP1 KO cancer cells compared to control cancer cells when cocultured with macrophages." (PMID 40595560, 2025). "Live cell imaging revealed increased colocalization of ATG9A-RFP and CAVIN2-GFP in cancer cells co-cultured with macrophages, a finding further supported by co-immunoprecipitation experiments." (PMID 40595560, 2025). "Mammalian ATG9A is the only transmembrane protein in the core ATG protein, and its dysregulation is related to cancer." (PMID 37782756, 2023). "Here, we show that similarly to GABARAPL1, ATG9A was up-regulated in TNBC and its inhibition decreased cancer phenotypes and abilities." (PMID 30563263, 2018). "However, due to the low number of patients presenting a cancer recurrence, we were not able to correlate the risk of recurrence to the difference of ATG9A expression levels between patients presenting a low or a high ATG9A mRNA expression." (PMID 30563263, 2018).
cancer (continued). "We then inhibited ATG9A expression in the TNBC cell line MDA-MB-436, and observed that ATG9A inhibition led to an inhibition of in vitro cancer features, such as proliferation and invasion." (PMID 30563263, 2018). "ATG9A and ATG2s were not involved in regulating PI4P levels in multiple cancer cell lines with RAS mutations." (PMID 40055523, 2025). "Despite these changes, calreticulin knockdown did not affect the cancer cell response to CAR-Ms in either control or ATG9A KO OVCAR-8 cells, indicating these are likely secondary changes." (PMID 40595560, 2025). "The combination of Trastuzumab and CSF1R inhibition to deplete non-cytotoxic macrophages significantly enhances ATG9A KO cancer cell killing in vivo." (PMID 40595560, 2025). "This suggests that the role of ATG9A in regulating cancer cell response to macrophages is not ESCRT-dependent." (PMID 40595560, 2025). "Furthermore, while autophagy is a critical process for cancer cell survival and has been highlighted in numerous CRISPR screens as a key regulator of immune responses, our studies indicate that ATG9A’s role in macrophage-mediated membrane repair operates independently of canonical autophagy." (PMID 40595560, 2025). "These in vitro data confirmed that ATG9A was necessary for the aggressive character of this cell line and that a high expression of this gene might be considered as a biomarker of TNBC even if ATG9A was also expressed at a lower level in LumA cancers." (PMID 30563263, 2018). "Flow cytometry analysis showed that ATG9A KO did not alter the expression of key phagocytosis checkpoints (MHC-I, PD-L1, CD24, CD47) or the CAR target EphA2, suggesting ATG9A regulates cancer cell susceptibility to macrophage killing through a specific and independent mechanism." (PMID 40595560, 2025).
infection (6 papers, 2018 to 2025). The state of being infected such as from the introduction of a foreign agent such as serum, vaccine, antigenic substance or organism. "Because sphingolipid availability has been associated with infection-induced Golgi redistribution, we investigated ceramide acquisition during the infection in ATG9A-KO and Wt cells." (PMID 37707289, 2023). "Although the upregulation mechanisms of STING signaling in ATG9A-KO MEF remain unknown, we speculate that the infection-induced STING signaling under ATG9A deficiency is regulated differently between human and mouse cells." (PMID 37707289, 2023). "In this case, we explored the link between Rab11a and ATG9A at 10 h after infection, as the GFP-Rab11 DNlow cells produce low levels of viral particles before this period (by plaque assay)." (PMID 37983294, 2023). "At 8 h of infection, viral inclusions produced by PA-mNeonGreen were rounded in control cells and became tubular upon ATG9A depletion." (PMID 37983294, 2023). "TGN46, a trans-Golgi marker, also showed the same redistribution after the infection, which was suppressed in ATG9A-KO cells." (PMID 37707289, 2023). "When ATG9A-KO and wild-type (Wt) HeLa cells were infected with C. trachomatis serovar L2, the infection efficiency (ratio of cells containing the inclusion) was similar to that in Wt cells." (PMID 37707289, 2023). "In infection, ATG9A mediates the removal of Rab11a-recycling endosomes carrying vRNPs from microtubules." (PMID 37983294, 2023). "While several ATG proteins have been directly implicated in these processes, there are few reports about the role of ATG9A in human disease, infection, and immunity." (PMID 30917996, 2019). "The levels of redistribution were similar in Wt cells, ATG9A-overexpressing Wt cells, and M33-overexpressing Wt cells, suggesting that the overexpression does not significantly modify infection-associated Golgi redistribution." (PMID 37707289, 2023). "As ATG9A is localized in the Golgi, endosomes, and plasma membrane (29, –, 32), we examined whether ATG9A is relevant in the infection-induced Golgi redistribution." (PMID 37707289, 2023). "Overall, these data support a role for ATG9A and PI4K2A recruitment to the site of pathogen infection to mediate membrane repair and restrict pathogen infection and a regulation of these events by ARFIP2." (PMID 40460835, 2025). "Furthermore, ATG9A role in viral inclusion formation seems to be independent from full autophagy pathway activation, even though we acknowledge that the pathway may be initiated in infection." (PMID 37983294, 2023). "A role of ATG9A trafficking during the infection was inferred from the observation that delta36AA did not restore either Golgi-redistribution or infectious progeny." (PMID 37707289, 2023). "Infection induced a gradual loss of ATG9A from the Golgi, as the colocalization between ATG9A and Golgi matrix protein GM130 decreased throughout infection (mean ± SEM of Pearson R value: Mock 0.411 ± 0.015, 4 h 0.400 ± 0.015, 6 h 0.318 ± 0.018, 8 h 0.281 ± 0.014, 14 h 0.242 ± 0.015)." (PMID 37983294, 2023). "ATG9A-KO cells showed no infection-induced redistribution of the Golgi from the perinuclear region to inclusion, which was restored by re-expressing the mutant but not the ATG9A mutant lacking an N-terminal adapter protein-binding domain." (PMID 37707289, 2023). "However, the gene expression of IFN-β in ATG9A-KO cells was significantly lower than in Wt cells irrespective of the infection, and ATG9A re-expression did not restore IFN-β expression, the reason for which cannot be explained at present." (PMID 37707289, 2023). "Moreover, we showed that the absence of ATG9A staining at the Golgi at later stages of infection is due to protein relocation and is not due to degradation." (PMID 37983294, 2023).
infection (continued). "Therefore, we investigated whether ATG9A participates in Golgi fragmentation, which has been reported to occur when Cdu1, a Chlamydia protein, is exogenously expressed in culture cells without infection." (PMID 37707289, 2023).
bacterial infection (2 papers, 2024 to 2025). "Our results identify a role for mobilized ATG9A vesicles and ARFIP2 in lysosome homeostasis after damage and bacterial infection." (PMID 40460835, 2025). "Therefore, we sought to confirm whether ATG9A and ATG9B are critical for autophagy induction during bacterial infection." (PMID 38706859, 2024).
ATG9A also shares sentences with these, for which no sentence is quoted: neurodegenerative disease (2 papers); acute kidney injury (1); Alzheimer disease (1); amyloid (1); asthma (1); autism (1); co-infection (1); cutaneous squamous cell carcinoma (1); gnathodiaphyseal dysplasia (1); heart failure (1); hypertrophic cardiomyopathy (1); liver disease (1); lymph node metastasis (1); male infertility (1); melanoma (1); neuroaxonal dystrophy (1); non-small cell lung carcinoma (1); nutritional deficiency (1); ovarian serous cystadenocarcinoma (1); Parkinson (1); preeclampsia (1); protein folding disorders (1); schizophrenia (1); viral infection (1).